BUB3 (BUB3 mitotic checkpoint protein)
Diseases named in the same sentence as BUB3 in open-access papers (continued):
Sharing a sentence is not in itself a finding about the gene and the disease.
tumor (28 papers, 2013 to 2025). "The expression of the BUB3 protein was found to be significantly upregulated in the nuclear membrane of the tumor cells associated with LUAD." (PMID 36787437, 2023). "This analysis included two or three tumor samples from each patient and demonstrated that patients with decreased levels of nuclear BUB3 in all analyzed samples were at increased risk of recurrence." (PMID 31801961, 2020). "The abnormal expression of Bub3 gene in a large number of tumors is closely associated with the regulation of tumor cell proliferation, apoptosis, and the cell cycle, and it also plays an important role in the occurrence, progression, metastasis, and prognosis of tumors." (PMID 34882895, 2022). "For instance, miR-664b-3p has been shown to suppress tumor cell proliferation and migration by targeting BUB3, a mitotic checkpoint protein." (PMID 40724871, 2025). "Hyperactivation of the YY2/BUB3 axis delays mitosis, increases chromosomal instability beyond tolerable thresholds, and induces tumor cell death, thereby enhancing drug sensitivity." (PMID 41440189, 2025). "When analyzed according to MSI and MSS status, adjusted for tumor location (right vs. left), BUB3, CDKN1A (p21), and RRM2 were significantly more upregulated in MSI tumors than in MSS tumors." (PMID 41440189, 2025). "Our findings revealed that the expression levels of TOP3A, SRC, and BUB3 were significantly elevated in the tumor groups of both the TCGA and GEO cohorts." (PMID 38825615, 2024). "Further analysis showed that overexpression of BUB1B, BUB1 and BUB3 promoted tumor cell proliferation and metastases by disturbing the spindle assembly checkpoint (SAC) in the mitosis." (PMID 37228122, 2023). "Concerning BUB3, an immunohistochemical expression was present in most of the cases, with staining homogenously distributed within tumor islands." (PMID 36428310, 2022). "PKM2 phosphorylates Bub3 at Tyr207 and recruits the complex Bub3-Bub1 to Blinkin known as the outer kinetochore protein, promoting chromosomal segregation and growth of tumor cells." (PMID 36077431, 2022). "The BUB3 was present in all cases, appearing in the nucleus of tumor cells, although staining was detected also in the tumor cytoplasm of four cases (8.8%)." (PMID 36428310, 2022). "A tumor suppressor role has been suggested for Bub3 in a Drosophila melanogaster tumorigenesis model derived from knocking down SAC genes." (PMID 35631670, 2022). "Significant results were only obtained for two of the series for cytoplasmic BUB3 and one series for nuclear BUB3, which necessitates analyses of multiple tumor samples for this protein." (PMID 31801961, 2020). "We observed 78 (32%) patients with ≥1 cytoplasmic BUB3 positive tumor area and 126 (52%) patients with ≥1 tumor area with decreased levels of nuclear BUB3." (PMID 31801961, 2020). "In analysis of multiple tumor areas, prognostic value was observed for cytoplasmic BUB3, CCNB1, and PTTG1." (PMID 31801961, 2020). "This complex (BUB1/BUBR1/BUB3) is necessary for correct balance of kinase-phosphatase balance during mitosis and has been proven to have a role in chromosome instability and tumor progression as well." (PMID 31311505, 2019). "c-Src-mediated DMAP1 Y246 phosphorylation promotes tumour cell survival through inhibition of Bub3/DMAP1 interaction under mitotic arrest." (PMID 30553276, 2018). "Collectively, these data indicated the inhibitory effect of DMAP1 Y246 phosphorylation on Bub3/DMAP1 interaction promoted tumour development." (PMID 30553276, 2018). "Together, these results suggest that defects in the YY2/BUB3 pathway could contribute to CIN induction in tumor cells, most plausibly due to impaired SAC activity." (PMID 38682484, 2024). "Furthermore, it is revealed that YY2/BUB3‐mediated excessive CIN causes higher cell death rates and drug sensitivity, whereas residual tumor cells that survived DNA damage‐based therapy have moderate CIN and increased drug resistance." (PMID 38682484, 2024).
tumor (continued). "In conclusion, this study demonstrated that miR-664b-3p could serve as a tumor-inhibitor miRNA in the progression of CC via suppressing the expression of the BUB3, which was an abnormal expression in the CC patients’ tissue." (PMID 35156516, 2022). "Furthermore, a Bub3 spindle checkpoint protein has been shown to act as a tumor suppressor after apoptosis inhibition and mediate cell cycle arrest after paclitaxel treatment." (PMID 35056723, 2022). "BUB3 (n = 244,616 samples) was expressed in the nuclei of both benign epithelial and tumor cells." (PMID 31801961, 2020). "The lack of significant results may be explained by the fact that only one block was included in the analysis of mRNA, as significant results were obtained for nuclear BUB3 in the analysis that considered intra-tumor heterogeneity." (PMID 31801961, 2020). "In another study, PKM2 was shown to regulate Bub3 to affect the cell cycle in tumor cells." (PMID 25788265, 2015). "Analysis of mice with reduced levels of Bub3 has shown that mice have significant increases in the number of aneuploid fibroblasts, and are predisposed to chemical-induced lung tumorigenesis rather than spontaneous tumor development." (PMID 35631670, 2022). "This study identifies the novel role of YY2 in modulating BUB3‐mediated SAC activity and CIN, as well as YY2/BUB3‐mediated SAC activity and CIN levels role in determining tumor cell fates." (PMID 38682484, 2024). "Above all, these results suggest Bub3/DMAP1 complex act as a repressive modulator of transcription for anti-apoptotic genes under mitotic stress and its effect is impaired in tumour cells with high levels of DMAP1 pY246." (PMID 30553276, 2018). "BUB3, DHFR, RRM1, and SRPK1 were also expressed in immune cells of GC's tumor microenvironment." (PMID 39895799, 2025). "Finally, we used the ssGSEA method to determine the correlations between ESPL1, AURKB, BUB3, and FAM83D and 24 types of tumor-infiltrating immune cells." (PMID 35646670, 2022). "In the same tumor tissue, the expression levels of BUB1, BUB1, and Bub3 gene showed the same trend." (PMID 34882895, 2022). "Meanwhile, we also found that BUB3 can negatively regulate B lymphocytes, and BUB1 and BUB1B inhibit immune responses by promoting the secretion level of checkpoint molecules of the immune system, leading to immune escape of tumor cells." (PMID 35493295, 2022). "Tumors having both positive and negative tumor areas for cytoplasmic BUB3 (30%), CCNB1 (28%), or PTTG1 (35%) were considered heterogeneous." (PMID 31801961, 2020). "Increased BUB3 expression was observed in tumor tissues compared to in paired non-malignant lung tissues (P = 2.8 × 10-8)." (PMID 28977903, 2017). "Optimal phenotypic pre-selection, including genetic or histologic abnormalities in the tumor, or even the presence of additional congenital features as we recently identified in individuals with BUB1 and BUB3 abnormalities, may limit this heterogeneity." (PMID 26901136, 2016). "Similarly, BubR1-insufficient and Bub3/Rae1-haploinsufficient mice do neither show increased spontaneous tumor formation." (PMID 39466849, 2024). "Currently, there is not much research on how Bub3 promotes tumor development." (PMID 34882895, 2022). "In contrast, haploinsufficiency of Bub3 or Rae1 did not result in increased tumorigenesis, and some mouse models even showed decreased tumor formation when challenged with carcinogens, suggesting that the relationship between impaired SAC signaling, aneuploidy and tumor onset is complex." (PMID 26015801, 2015).
infection (2 papers, 2009 to 2022). The state of being infected such as from the introduction of a foreign agent such as serum, vaccine, antigenic substance or organism. "Our results provided new insights into the mechanism underlying the ARV-manipulated cell cycle via hijacking host mitotic protein Bub3 during infection." (PMID 36366482, 2022). "The infection of the Vero cells by ARV downregulated the Bub3 expression, while the knockdown of Bub3 alleviated the p17-modulated cell-cycle arrest during ARV infection." (PMID 36366482, 2022). "In this study, it was found that targeting Bub3 by ARV p17 might be a common strategy to manipulate the cell-cycle progression during ARV infection, and the interconnection of Bub3 and p17 may also affect the formation of progeny virions." (PMID 36366482, 2022). "Likewise, a moderate decrease in the Bub3 levels had also been observed in the ARV-infected cells at 24 and 48 h post infection." (PMID 36366482, 2022).
immune dysfunction (1 paper, 2024). "The increased expression of BUB3 suggests increased proliferation of HIV-specific CD8 T cells in progressors, which could be indicative of recent antigen exposure and high CD8 T cell turnover and contribute to immune activation, exhaustion and immune dysfunction." (PMID 39356699, 2024).
BUB3 also shares sentences with these, for which no sentence is quoted: pancreatic adenocarcinoma (3 papers); adrenocortical carcinoma (2); hepatic carcinoma (2); Alzheimer disease (1); benign prostatic hyperplasia (1); bladder tumors (1); brain edema (1); brain tumor (1); chondrosarcoma (1); clear cell kidney carcinomas (1); esophageal squamous cell carcinoma (1); Ewing sarcoma (1); familial colorectal cancer (1); malignant fibrous histiocytoma (1); metastatic disease (1); migraine (1); pancreatitis (1); pituitary tumor (1); pulmonary arterial hypertension (1); synovial sarcoma (1).